ZNF629 (zinc finger protein 629)
Description:
May be involved in transcriptional regulation.
Synonyms: KIAA0326; ZNF65; ZNF
Tractability: PROTAC: UniProt records ubiquitination sites on it; ubiquitination databases record sites on it; its protein half-life has been measured.
Gene: Protein-coding gene on chromosome 16 (30,778,456 to 30,787,205, reverse strand). Ensembl gene ENSG00000102870.
Subcellular location: Nucleus
Subcellular location (Human Protein Atlas): Nucleoplasm; Golgi apparatus
Gene Ontology:
Molecular function: protein binding; transcription cis-regulatory region binding
Biological process: regulation of transcription by RNA polymerase II
Cellular component: nucleoplasm; nucleus
Genetic constraint (gnomAD): Loss-of-function variants: 9 observed, 55.95 expected, observed/expected ratio (o/e) 0.16, 90% interval 0.096 to 0.28. The upper end of that interval is the gene's LOEUF score, 0.28, which puts it in group 1 of 6, group 1 being the genes least tolerant of losing a copy. Missense variants: 853 observed, 1,121.4 expected, observed/expected ratio (o/e) 0.76, 90% interval 0.72 to 0.81. Synonymous variants: 509 observed, 483.23 expected, observed/expected ratio (o/e) 1.05, 90% interval 0.98 to 1.13.
Homologues: Orthologues: chimpanzee ZNF629 (99% identical), macaque ZNF629 (97% identical), dog ZNF629 (93% identical), pig ZNF629 (91% identical), mouse Zfp629 (89% identical), rat Zfp629 (89% identical), rabbit ZNF629 (87% identical), guinea pig Znf629 (24% identical). Paralogues in human: ZNF658 (30% identical), ZNF33B (29% identical), ZNF229 (29% identical), ZNF235 (29% identical), ZNF189 (29% identical), ZNF484 (29% identical), ZNF227 (28% identical), ZNF41 (28% identical), ZNF197 (28% identical), ZNF841 (28% identical), ZNF605 (28% identical), ZNF16 (28% identical), and 164 more.
Diseases named in the same sentence as ZNF629 in open-access papers:
ZNF629 is named in the same sentence as 2 diseases in open-access papers, as found by Europe PMC text mining. Sharing a sentence is not in itself a finding about the gene and the disease. The quoted sentences say what the papers report.
Immunodeficiency (1 paper, 2023). Failure of the immune system to protect the body adequately from infection, due to the absence or insufficiency of some component process or substance. "ZNF629 is known to cause immunodeficiency and ZKSCAN3 is a master repressor of autophagy." (PMID 38025778, 2023).
ZNF629 also shares sentences with these, for which no sentence is quoted: tumor (1 paper).